FOLR1 (folate receptor alpha)
Diseases named in the same sentence as FOLR1 in open-access papers (continued):
Sharing a sentence is not in itself a finding about the gene and the disease.
breast carcinoma (continued). "The mRNA expression of FOLR1 was examined by real-time RT-PCR in normal human mammary epithelial cells (HMECs) and in bronchial epithelial cells (BEAS-2B), which were used as controls for breast cancer and NSCLC cells, respectively." (PMID 33535554, 2021). "MORAb-202 exhibited an inhibition of cell proliferation with specific selectivity toward FOLR1-expressing breast cancer cell lines but not FOLR1-expressing NSCLC lines." (PMID 33535554, 2021). "The in vivo targeting ability of each nanoprobe was established by imaging mice bearing subcutaneous tumors expressing one of three biomarkers of relevance in breast cancer: caveolin 1 (CAV1), C-X-C chemokine receptor type 4 (CXCR4), and Folate Receptor alpha (FRα)." (PMID 33172421, 2020). "The authors focused on the folate receptor alpha (FRA), which is a glycosylphosphatidylinositol (GPI)-linked protein that is frequently overexpressed in various malignant tumors of epithelial origin, including ovarian, lung, and breast cancer, while largely absent from normal tissues." (PMID 36005497, 2022). "Moreover, additional studies may provide insight into whether FOLR1 expression is associated with a particular subtype of triple negative cancer and what the biological consequences of FOLR1 overexpression are in breast cancer?" (PMID 25816016, 2015).
folate deficiency (32 papers, 2007 to 2025). A nutritional condition produced by a deficiency of FOLIC ACID in the diet. "Cerebral folate deficiency caused by folate receptor alpha (FRα) autoantibodies disrupts brain folate transport, leading to language delay, poor attention, and sometimes seizures by impairing neurodevelopment and neurotransmitter synthesis." (PMID 41020843, 2025). "Cerebral folate deficiency, caused by folate receptor autoantibodies or germline mutations in FOLR1 or SLC46A1, and insufficient folate intake around and during pregnancy have been associated with an increased risk of neural tube defects." (PMID 40792046, 2025). "Cerebral folate deficiency due to folate receptor alpha autoantibodies blocks folate entry into the brain, disrupting myelination, neurotransmitter synthesis, and neuronal stability." (PMID 41020843, 2025). "Cerebral folate deficiency is a rare autosomal recessive disorder caused by mutations in the FOLR1 gene." (PMID 40217438, 2024). "Genetic factors (e.g., MTHFR, FOLR1 SNPs), folate deficiency, infections during pregnancy, maternal diabetes, obesity." (PMID 39796560, 2024). "Loss of function in FOLR1 results in a cerebral folate deficiency, indicating that this is the major transporter." (PMID 39337690, 2024). "De novo loss of function variants of the gene CIC can contribute to cerebral folate deficiency by downregulating FOLR1 expression." (PMID 38828282, 2024). "Folic acid is not recommended because of the potentially low activity of dihydrofolate reductase in cerebral folate deficiency, and because of its tight binding to folate receptor alpha that results in reduced cerebral transport of 5-methyltetrahydrofolate." (PMID 36330595, 2023). "The siblings we describe here provide strong support for the effectiveness and importance of folinic acid treatment initiation at a very early age in patients with pathogenic variants in FOLR1 and neurodegeneration due to cerebral folate deficiency." (PMID 37443037, 2023). "The folate receptor alpha (FRα) is expressed in the choroid plexus as well, and its loss of function results in an autosomal recessive disorder that solely leads to cerebral folate deficiency." (PMID 36770817, 2023). "For example, some severe neurological conditions are caused by autoantibodies, or abnormal genes for folate receptor alpha (FOLR1) that block the transfer of folate from the blood into the brain, resulting in a severe cerebral folate deficiency." (PMID 35736408, 2022). "Thiamine and biotin treatment in biotin- or thiamine-responsive encephalopathy (mutations in SLC19A3), folinic acid in cerebral folate deficiency (mutations in FOLR1), and creatine in cerebral creatine deficiency (mutations in SLC6A8) are other examples." (PMID 33726816, 2021). "On comparing the effect of folate-deficiency with either state of B12 in comparison to control, an increase in expression of FOLR1 gene was observed (BNFN vs BNFD, BDFD, BOFD)." (PMID 31772242, 2019). "Folate deficiency and folate receptor alpha autoantibodies (FRα-AuAb) have been associated with pregnancy-related complications and neurodevelopmental disorders." (PMID 27011008, 2016). "It is also possible that an increase of the small subunit is actually a feedback response to intracellular oxidative stress caused by the Folr1 gene ablation and/or folate deficiency." (PMID 18028541, 2007). "Additionally, autoantibodies directed against folate receptor alpha (FRα) can impede folate transport into the brain, causing cerebral folate deficiency even when peripheral levels appear adequate." (PMID 41020843, 2025). "To date, 19 cases of cerebral folate deficiency due to FOLR1 gene mutations have been reported." (PMID 40217438, 2024). "Moreover, the Folr1 auto-antibodies or folate deficiency in CSF may lead to server development disorders of in children nervous system." (PMID 28416738, 2017).
folate deficiency (continued). "The cerebral folate receptor alpha (FRα) transports 5-methyltetrahydrofolate (5-MTHF) into the brain; low 5-MTHF in the brain causes cerebral folate deficiency (CFD)." (PMID 34834493, 2021). "In the present study, folate deficiency resulted in increased expression of folate transporters RFC, PCFT and FOLR1 required to mediate transport into the cell however, over supplementation of folate was associated with a decrease in the expression." (PMID 31772242, 2019). "Thus, the etiology of primary cerebral folate deficiency includes the presence of autoantibodies against the folate receptor (FR1) and mutations in the FOLR1 gene, which encodes the FR1 protein." (PMID 40217438, 2024). "One further cause of cerebral folate deficiency, independent of CSF abnormalities, and identified as a cause of childhood epilepsy and autism, is autoantibodies to FOLR1." (PMID 39337690, 2024). "Analyzing the effect of folate deficiency with either state of B12 in comparison to control revealed an increase in the expression of FOLR1 gene in all fetal tissues regardless of sex (BNFN vs BNFD, BDFD, BOFD)." (PMID 31772242, 2019). "Under the conditions of B12 over-supplementation, combination with folate deficiency (BOFD) increased the expression in fetal tissues whereas that with folate normal and over-supplementation (BOFN and BOFO) increased FOLR1 in the brain and kidney (female) in comparison to BNFN." (PMID 31772242, 2019). "Cerebral folate deficiency is reported in several types of mitochondrial disease, including POLG mutations, ranging from mild deficiency to more severe forms that can mimic primary folate disorders, such as those due FOLR1 mutations." (PMID 30167885, 2018). "FOLR1 gene mutations, causing cerebral folate deficiency, lower CSF folate but not blood levels." (PMID 39204177, 2024). "In St6, there was phenotypic overlap with cerebral folate deficiency due to FOLR1‐mutations, in which the GPI‐anchored folate receptor alpha fails to provide folate to the brain." (PMID 32588908, 2020).
lung carcinoma (28 papers, 2012 to 2025). "Folate-conjugated miR-34a (folate–miR-34a) has demonstrated promising anti-tumor efficacy in breast and lung cancers by targeting folate receptor α (FOLR1)." (PMID 38396800, 2024). "A successful example is developing folate-conjugated miR-34a (folate–miR-34a) to target breast and lung cancers via folate receptor α (FOLR1)." (PMID 38396800, 2024). "Its overexpression in various solid malignancies including ovarian and lung cancer makes FOLR1 an attractive target for both small molecule- and antibody-based diagnostic and therapeutic reagents." (PMID 31497024, 2019). "Our group has recently reported the predictive value of FOLR1 expression in NSCLC patients receiving pemetrexed-based chemotherapy, indicating FOLR1 as potent biomarker in lung cancer." (PMID 27064343, 2016). "Similarly, KRT6A, MIR31HG, and FOLR1 have been found to enhance lung cancer proliferation and may be potential therapeutic targets." (PMID 38926418, 2024). "Folate receptor alpha (FRα) is a glycosylphosphatidylinositol (GPI)-anchored membrane protein that is highly expressed in epithelial ovarian, breast, and lung cancers." (PMID 38667465, 2024). "Folate-receptor 1 (FOLR1) and prostate specific membrane antigen (PSMA) are overexpressed in solid tumors including lung cancer, prostate cancer, and renal cell carcinoma." (PMID 37296863, 2023). "The presented mechanism of enhancement of the WT1TCR signaling by NFAT-regulated CAR can be modified to target different WT1-positive tumors, such as ovarian and lung carcinoma, by using inducible CAR specific to surface antigens such as mesothelin, Her2, or folate receptor alpha." (PMID 40735486, 2025). "For lung cancer, major pathways included mitotic regulation, metabolic reprogramming, and tight junction integrity, having highly enriched genes such as MYBL2 (driving cell cycle) and FOLR1 (facilitating tumor growth through folate metabolism)." (PMID 40565055, 2025). "Among these, folate receptor alpha (FRα) is highly expressed in non-mucinous tumors of epithelial origin, including ovarian, breast, and lung cancers." (PMID 37509354, 2023). "Folate receptor-alpha (FRα) is highly expressed in non-mucinous tumors of epithelial origin including ovarian, breast, and lung cancers and expressed at low levels on the apical surface of a subset of polarized epithelial cells including the parotid, kidney, lung, thyroid, and breast." (PMID 27439908, 2016).
peritoneal cancer (22 papers, 2017 to 2025). A peritoneum cancer that is located in the inside of the abdomen. "“Folate receptor alpha (FRα)-positive, platinum-resistant epithelial ovarian, fallopian tube, or primary peritoneal cancer who have received one to three prior treatments”." (PMID 40265416, 2025). "Mirvetuximab soravtansine (MIRV) is an ADC that was approved by the FDA in 2022 for the treatment of folate receptor alpha-positive, platinum-resistant ovarian, fallopian tube or peritoneal cancer." (PMID 40501953, 2025). "It was granted accelerated approval by the FDA in November 2022, for adult patients with folate receptor alpha (FRα) positive, platinum-resistant epithelial ovarian, fallopian tube, or primary peritoneal cancer who have received one to three prior systemic treatment regimens." (PMID 37631374, 2023). "Validated specimens for FOLR1 immunohistochemical assay include formalin-fixed, paraffin-embedded (FFPE) tissue samples from primary ovarian, fallopian tube, and peritoneal cancers." (PMID 40508029, 2025). "This immunohistochemical test utilizes a mouse monoclonal anti-FOLR1 antibody (clone FOLR1-2.1) to detect folate receptor alpha (FOLR1) protein expression in formalin-fixed, paraffin-embedded (FFPE) tissue specimens from epithelial ovarian, fallopian tube, or primary peritoneal cancers." (PMID 40508029, 2025).
ovarian tumor (20 papers, 2012 to 2025). "In the co-culture of adherent EpCAM-positive ovarian tumor cells, which highly expressed FOLR1, with autologous PBL from patient #1, stimulation with ETA-067 and rIL-2 induced enhanced lysis (90%) of the tumor cells." (PMID 40755782, 2025). "Understanding the heterogeneity of FOLR1 expression in ovarian tumors is crucial for selecting effective FOLR1-targeting therapeutics." (PMID 40029935, 2025). "FOLR1 expression was markedly higher in primary ovarian tumour samples compared to a range of normal tissues." (PMID 36402875, 2023). "We found that expression of FOLR1 is significantly reduced in drug-resistant ovarian tumors compared to drug-sensitive tumors." (PMID 29433550, 2018). "The transcriptomic analysis shows that the human ovarian tumor cells SKOV3 and OVCAR3 expressed the FOLR1 isoform and that the different isolated immune cells expressed the FOLR2 isoform." (PMID 32326210, 2020). "Transcriptomic analyses showed high FOLR1 (FRα) expression in primary ovarian tumours, minimal expression in normal fallopian tubes and none in normal skin or non‐malignant ovarian tissues." (PMID 40045925, 2025). "In normal ovarian tissue, the expression of FOLR1 is restricted to luminal surfaces but is ubiquitous in ovarian tumour tissue, mostly in tumours of non-mucinous histology." (PMID 35031764, 2022). "FOLR1 and MSLN were highly and specifically stained on the surface of ovarian tumor cells, while almost no significant staining was observed for FOLR1 or MSLN in normal ovarian tissue specimens." (PMID 34803504, 2021).
serous ovarian cancer (19 papers, 2012 to 2025). "Folate receptor alpha (FRα) is a high-affinity folate transporter overexpressed in various epithelial malignancies, particularly high-grade serous ovarian carcinoma." (PMID 40869006, 2025). "Folate receptor alpha (FRα) is a glycosylphosphatidylinositol‐anchored protein that is minimally expressed in normal tissues but is overexpressed in more than 80% of serous ovarian cancer." (PMID 39526448, 2024). "Other than folate receptor alpha (FRα), NaPi2B, a protein involved in sodium-dependent phosphate transport, is found in approximately two thirds of high-grade serous ovarian cancer patients." (PMID 39590153, 2024). "In either case, the overexpression of FOLR1 was reported in serous ovarian carcinoma describing clinicopathological characteristics and outcomes, as well as the relationship between FOLR1 and chemoresistance." (PMID 33800113, 2021). "The folate receptor alpha (FRα) is overexpressed in the majority of high-grade serous ovarian cancers and has been proposed as a candidate vaccine antigen." (PMID 33057068, 2020). "This study evaluated 91 specimens of serous ovarian carcinomas, and the results showed that over-expression of FOLR1 is a poor prognostic factor for disease-free survival and has a negative impact on overall survival of patients." (PMID 23319948, 2012). "FOLR1 over-expression was confirmed in serous ovarian carcinoma in previous studies detailing clinicopathologic features and outcomes, as well as the relationship between FOLR1 and chemoresistance." (PMID 23319948, 2012). "Folate receptor alpha (FRα) is an antigen found in approximately 60-90% of serous ovarian cancers." (PMID 38248092, 2023). "Previous work within our laboratory, based on immunohistochemical detection of folate receptor alpha (FRA), has shown a strong correlation between ovarian serous carcinomas (EOC) and normal fallopian tube as well as fallopian adenocarcinoma with respect to expression of this receptor." (PMID 25971554, 2015).
gastric cancer (17 papers, 2018 to 2026). A primary or metastatic malignant neoplasm involving the stomach. "To understand the mechanism underlying the poor prognosis of gastric cancer expressing FOLR1 at a high level, we examined the abundance of FOLR1 mRNA and FOLRα protein in various human gastric cancer cell lines by RT‐qPCR analysis and immunoblot analysis, respectively." (PMID 34185411, 2021). "Five studies evaluated the feasibility of in vivo LNMs detection using this dye in ovarian, endometrial, and gastric cancer, which also targets folate receptor alpha (FRα)." (PMID 40282528, 2025). "qRT-PCR showed significant overexpression of FOLR1 in gastric cancer blood samples compared to control samples, with a median fold change of approximately 14.18 times." (PMID 38915965, 2024). "In conclusion, our study highlights the significant overexpression of FOLR1 and FOLR2 in gastric cancer and its association with adverse clinicopathological features, particularly for FOLR1." (PMID 38915965, 2024). "While FOLR1 shows potential as a biomarker for gastric cancer due to its overexpression, further studies are needed to fully elucidate the therapeutic and prognostic implications of folate receptors in gastric cancer." (PMID 38915965, 2024). "This substantial increase, coupled with a very low p-value (0.002), suggests a potentially critical role of FOLR1 in the pathophysiology of gastric cancer." (PMID 38915965, 2024). "In the blood samples of gastric cancer patients, FOLR1 was overexpressed, with a median fold change of 14.18 times higher than in normal samples, a difference that is statistically significant." (PMID 38915965, 2024). "The few available CAR T cell-based studies in gastric cancer suggest folate 1 receptor (FOLR1) and NKG2D as relevant targets." (PMID 37173782, 2023). "Other antigens have been targeted with CAR-T cells in gastric cancer, including folate receptor 1 (FOLR1), claudin 18.2, HER2, and NKG2D." (PMID 36831396, 2023). "Other studies have shown modest antitumor response by FOLR1-CAR T cells in xenograft models of gastric cancer 29 and triple-negative breast cancer." (PMID 34803504, 2021). "The second study used the fact that folate 1 receptor (FOLR1) expression is overexpressed in gastric cancer in comparison to normal tissue." (PMID 31936611, 2020). "Folate receptor 1 (FOLR1) is overexpressed on the cell surface in over one-third of gastric cancer patients, but rarely is expressed in normal tissue." (PMID 29874279, 2018). "Both FOLR1-CAR KHYG-1, a natural killer cell line, and FOLR1-CAR T cells recognized FOLR1-positive gastric cancer cells in a MHC-independent manner and induced secretion of various cytokines and caused cell death." (PMID 29874279, 2018). "FOLR1 can be a key immunotherapy target against gastric cancer because more than one-third of patients with gastric cancer have FOLR1 expression." (PMID 29874279, 2018). "Conclusively, this is the first study to demonstrate that CAR KHYG-1/T cells targeting FOLR1 are effective against FOLR1-positive gastric cancer cells." (PMID 29874279, 2018). "In a cohort of 58 gastric cancer patients, immunohistochemical analysis was used to assess the expression of FOLR1 and FOLR2 and correlate these findings with various clinical and pathological variables such as age, gender, cancer stage, tumor site, liver involvement, and histological type." (PMID 38915965, 2024). "The significant differences observed between the histological subtypes of gastric cancer, specifically diffuse and intestinal types, in relation to FOLR1 and FOLR2 expressions, align with the growing body of evidence that suggests molecular heterogeneity within gastric cancer subtypes." (PMID 38915965, 2024). "Overall survival was significantly (P < .001) shorter for patients with a high level of FOLR1 expression in their tumors than in those with a low level, suggesting that FOLRα expression may be related to tumor aggressiveness in gastric cancer." (PMID 34185411, 2021).